RN7SKP294 (RN7SK pseudogene 294)
Gene: Miscellaneous RNA gene on chromosome 8 (49,330,210 to 49,330,547, forward strand). Ensembl gene ENSG00000199640.
Homologues: Orthologues: chimpanzee 7SK (99% identical). Paralogues in human: RN7SKP79 (72% identical), RN7SKP71 (72% identical), RN7SKP217 (71% identical), 7SK (71% identical), RN7SKP203 (69% identical), RN7SKP225 (69% identical), RN7SKP255 (69% identical), RN7SKP180 (69% identical), RN7SKP102 (69% identical), RN7SKP124 (69% identical), RN7SKP173 (69% identical), RN7SKP176 (69% identical), and 284 more.